KRAS (KRas proto-oncogene, GTPase)
Diseases named in the same sentence as KRAS in open-access papers (continued):
Sharing a sentence is not in itself a finding about the gene and the disease.
lung cancer (continued). "In this study, we reported for the first time honokiol induced apoptosis, G1 arrest, as well as autophagy mediated cell death in KRAS mutant lung cancer cells, and honokiol blocked KRAS mutant lung cancer cells growth by activating mitochondrial Sirt3 and suppressing HIF-1α expression." (PMID 28443025, 2017). "Thus, in three independent human lung cancer patient cohorts, we observed frequent expression of RANK protein in all lung cancer histotypes, and RANK positivity correlated with KRas mutations." (PMID 29118048, 2017). "Secondly, they hypothesize that a combination of MEK and FGFR inhibition would likely be a valid approach in the treatment of KRAS-mutant lung cancer." (PMID 28030802, 2017). "Consistent with previous reports, we demonstrated that Sirt3 was significantly downregulated in KRAS mutant lung cancer cells compared with normal lung cells, which could be enhanced by honokiol treatment." (PMID 28443025, 2017). "The multipeptide KRAS vaccine was immunogenic and efficacious in the primary prevention of KRAS-induced lung cancer, indicating that the approach potentially can be used to prevent other KRAS-driven cancers, either alone or in combination with other modalities." (PMID 29137294, 2017). "Using a LSL:KrasG12D/+; Lkb1flox/flox (LSL=Lox-stop-Lox) mouse model of lung cancer, we demonstrated previously that Lkb1 inactivation dramatically accelerated KRAS-driven lung cancer progression and changed the tumour spectrum from purely ADC to ADC and SCC26." (PMID 28387316, 2017). "Furthermore, knockout of HK2 suppressed tumor initiation and progression in KRAS-driven lung cancer and ErbB2-driven breast cancer mouse models." (PMID 29043013, 2017). "Regardless, our study provides further evidence for targeting to KRAS protein, which may contribute to the future study for lung cancer therapy." (PMID 29184501, 2017). "By optimizing competitive allele‐specific TaqMan PCR (CAST‐PCR), we assessed the copy number of mutated Kirsten rat sarcoma viral oncogene homolog (KRAS) and epidermal growth factor receptor (EGFR) alleles in the pre/post surgery plasma of 168 lung cancer patients." (PMID 28382702, 2017). "Honokiol was shown to induce G1 arrest and apoptosis to inhibit the growth of KRAS mutant lung cancer cells, which was weakened by an autophagy inhibitor 3-methyladenine (3-MA), suggesting a pro-apoptotic role of honokiol-induced autophagy that was dependent on AMPK-mTOR signaling pathway." (PMID 28443025, 2017). "Differences between the oncogenicity of specific Kras variants in our mouse model compared to their prevalence in human lung cancers indicate that factors other than the intrinsic oncogenicity of KRAS mutants likely influence their representation in the human disease." (PMID 29233960, 2017). "Furthermore, surprisingly, a more recent report has revealed that miR-193a-3p directly targets KRAS and inhibits tumor growth and metastasis in an ex vivo and in vivo lung cancer model." (PMID 29115941, 2017). "Moreover, ARS853 treatment led to significant reductions in PD-L1 surface protein expression in the KRAS mutant lung cancer cell line H358." (PMID 29246442, 2017). "For example, patients with TNBC or KRAS-mutant lung cancers may obtain optimal benefit from IGF1R inhibitor drugs." (PMID 29099049, 2017). "More extensive analysis of PD-L1 surface expression on multiple KRAS mutant lung cancer cell lines, both human and murine, revealed generally consistent PD-L1 downregulation after MEK and PI3K inhibition, suggesting that this regulatory pathway is of broad significance." (PMID 29246442, 2017).
lung cancer (continued). "We demonstrate that the multipeptide KRAS vaccine is immunogenic and efficacious in the primary prevention of KRAS-induced lung cancer, indicating that the approach potentially can be used to prevent other KRAS-driven cancers, either alone or in combination with other modalities." (PMID 29137294, 2017). "Thus, in mice, RANK expression is strongly induced in both oncogenic KRas-expressing pneumocytes in vitro and KRas-driven lung cancer cells in vivo, already observed at early stages of hyperplastic transformation." (PMID 29118048, 2017). "Taken together these data support a model where PDHK4 regulates KRAS signalling and its tumorigenic properties and suggest that inhibition of PDHK4 could represent a novel therapeutic strategy to target KRAS mutant colorectal and lung cancers." (PMID 28692044, 2017). "Recently, IL-6 blockade was shown to inhibit mutant KRAS driven lung cancer, indeed several studies have shown increased IL-6 expression in lung tumors with mutant KRAS —evidence of this relationship can also be observed from a parallel study on-going in our group." (PMID 28402963, 2017). "According to the results obtained on cbx7 null MEFs, the levels of KRAS protein were found downregulated in A549 cells (human lung carcinoma line), overexpressing the CBX7 protein, in which we found higher miR-155 levels with respect to the same cells transfected with the control vector." (PMID 28259135, 2017). "Furthermore, NOS2-deficiency decreased lung tumor growth and oncogenic Kras-mediated inflammatory response, and increased survival in a mouse model of lung cancer with conditional activation of mutant KRAS." (PMID 27367029, 2016). "Interestingly, our study showed that the GSK-3α knockdown highly suppressed the cell viability of KRAS-WT lung cancer cell lines, H1993 and H1437 cells, compared to KRAS-mutant lung cancer cell lines, H1734 (G13C) and A549 (G12S) cells." (PMID 27049759, 2016). "Our results support our hypothesis that Aurora kinases are important KRAS targets in lung cancer and suggest Aurora kinase inhibition as a novel approach for KRAS-induced lung cancer therapy." (PMID 26842935, 2016). "Similar mechanism results were obtained in several KRAS-mutant lung cancer cell lines." (PMID 27793187, 2016). "Nonetheless, effective targeted therapy options for lung cancer patients with KRAS mutations are currently lacking." (PMID 26842935, 2016). "Recently, using an HK2 conditional knockout mouse, a group showed that HK2 is required for tumor initiation and maintenance in mouse models of KRas-driven lung cancer, lending further evidence that HK2 is a key metabolic driver in cancer, and an attractive target in cancer biology." (PMID 27588472, 2016). "In this study we investigated Aurora A and Aurora B as potential KRAS targets in lung cancer." (PMID 26842935, 2016). "Our studies support exploration of PKCδ as a drug target in KRAS mutant lung cancer." (PMID 26918447, 2016). "There's a need for developing target therapies for KRAS mutant lung cancer and other tumors." (PMID 26840022, 2016). "In order to validate AURKA and/or AURKB as therapeutically relevant KRAS targets in lung cancer, we treated A549 and H358 cells, as well as two different lung cell based models of gain-of-function of KRAS with a dual Aurora kinase inhibitor and performed functional in vitro assays." (PMID 26842935, 2016). "In conclusion, our results support our hypothesis that Aurora kinases are important KRAS targets in lung cancer and suggest Aurora kinase inhibition as a novel and specific approach to be explored for KRAS-induced lung cancer therapy." (PMID 26842935, 2016). "Many lung cancer driver gene mutations have been identified, such as EGFR, KRAS, ROS, EML4-ALK." (PMID 27223066, 2016).
lung cancer (continued). "KRAS and EGFR represent two most commonly mutated oncogenes in lung cancer with distinct biology." (PMID 27485414, 2016). "Further studies are warranted to elucidate the clinical and/or biological significance of acquired PIK3CA mutations, KRAS mutations and uncommon EGFR (other than p.T790M) mutations as well as other co-existing resistance mutations in TKI-resistant lung cancers." (PMID 27304188, 2016). "TBK1 was described as co-synthetic lethal in KRAS mutant lung cancer but, so far, it has not been associated with EGFR mutant cancer." (PMID 27613601, 2016). "Moreover, an interesting study reported that specific KRAS mutation regulates EZH2 protein expression through the PI3K/AKT and/or MEK/ERK signaling pathways in lung cancer." (PMID 27494834, 2016). "Together these experiments demonstrate that ATM inactivation by shRNA knockdown or CRISPR/Cas9 knockout strongly sensitizes lung cancer cells to MEK inhibition even in the absence of KRAS or BRAF mutations." (PMID 27922010, 2016). "In concordance with these observations, our data suggest that EGFR/KRAS driven signaling might activate YAP1 leading to its nuclear translocation in lung cancers." (PMID 26716514, 2016). "Our study identifies OTUB1 as a key player in the pathogenesis of wt KRAS lung cancers." (PMID 26881969, 2016). "Ethnical origins and different risk factors for lung cancer might explain the distinct mutation profiles, as in the case of epidermal growth factor receptor (EGFR) and KRAS for Asians, Caucasians and Latins." (PMID 27098372, 2016). "Furthermore, targeting Aurora kinases by RNA interference reduces the oncogenic phenotype of KRAS mutant lung cancer cells in vitro and AURKA targeting slows tumor growth in vivo." (PMID 26842935, 2016). "Accumulation of EGFR and KRAS genetic alterations leads to the pathogenesis of lung cancer." (PMID 27863408, 2016). "Furthermore, a report in lung cancer demonstrated that KRAS(G12D)-induced CXCLs mediated tumorigenesis by recruiting inflammatory and endothelial cells." (PMID 26771140, 2016). "Preclinical studies have demonstrated that combining MEK inhibitors with PI3K inhibitors or BCL-XL may be an effective therapeutic strategy for KRAS mutant lung cancer." (PMID 27014419, 2016). "At this stage, it is unknown how DUOX1 silencing relates to different types of lung cancer or with specific mutations in EGFR, KRAS and so on." (PMID 27694834, 2016). "Consequently, GSK-3α knockdown significantly suppressed the cell viability of KRAS-WT lung cancer cell lines (H1993 and H1437), compared to KRAS-mutant lung cancer cell lines (H1734 and A549)." (PMID 27049759, 2016). "Therefore, a better understanding of the molecular pathways triggered by oncogenic KRAS in lung cancer is warranted, as it can identify new potential targets to be explored therapeutically." (PMID 26842935, 2016). "Additionally, NOS2/NO signaling is reported to mediate mutant KRAS-induced inflammation in lung cancer model, which is consistent with its role as an inflammatory mediator." (PMID 27367029, 2016). "KRAS-induced inflammation has been extensively examined in lung cancer." (PMID 27483433, 2016). "Oncogenic KRAS mutations increase ROS levels and overexpression of GLUT1 in lung carcinomas." (PMID 27863474, 2016). "However, pharmacologic inhibition of FAK kinase activity suppressed KRAS-driven lung adenocarcinomas, suggesting an involvement of FAK kinase activity in KRAS-driven lung cancer." (PMID 26274564, 2015). "For example, patients with triple negative breast cancer or KRAS-mutant lung cancers might benefit from IGF-1R inhibitor drugs." (PMID 26217584, 2015).
lung cancer (continued). "EGFR and KRAS somatic mutations, previously detected by SS, were confirmed by both pipelines either in SF and matched FFPE, validating the high specificity of the Ion AmpliSeq Colon and Lung Cancer panel for the identification of these mutations." (PMID 26633390, 2015). "We found that all lung cancer cells with mutant KRAS were sensitive to BEZ/GSK/TSA inhibition." (PMID 26158412, 2015). "In our retrospective quality assessment analysis of the NGS assay, KRAS mutations of less than 10% mutant alleles were observed in 5% of KRAS-mutated CRC specimens and in 14% of KRAS-mutated lung cancer specimens (data not shown)." (PMID 26517354, 2015). "Our results suggest that NASTRp may be a novel cancer therapy by inhibiting cell cycle as well as autophagy that will provide benefits for lung cancer treatment in advanced and/or KRAS mutant lung cancers." (PMID 25897662, 2015). "Serglycin core protein was detected only in the culture medium of aggressive cell lines such as A549, NCI-H23, and HCC827 lung cancer cells and DLD-1 colon cancer cells as well as MDA-MB-231 breast cancer cells as previously shown, which harbor KRAS or HER1/EGFR mutations." (PMID 26581653, 2015). "Of several different testing methods available, PCR followed by directed sequencing and amplification refractory mutation system (ARMS) are the two most commonly used diagnostic methods worldwide to detect mutations at KRAS exon 2 and EGFR kinase domain exons 18-21 in lung cancer." (PMID 27127615, 2015). "It is known that activating mutations in the HRAS homolog, KRAS, decrease gefitinib sensitivity in NSCLC, and that activation of the PIK3CA pathway also reduces tyrosine kinase inhibitor sensitivity in EGFR-mutant lung cancers." (PMID 25969993, 2015). "With the aim of improving therapeutic attempts for lung cancer harboring KRAS mutant, we found a multi-functional transcription factor inhibitor named Naphthol AS-TR phosphate (NASTRp), targeting the CREB-CBP complex, as a potent anti-cancer agent for lung cancer." (PMID 25897662, 2015). "In early stage lung cancer, KRAS mutations are neither of prognostic relevance nor are they predictive for the use of adjuvant chemotherapy." (PMID 26018876, 2015). "Taken together, these findings suggest that upstream inhibition of the EGFR/HER receptors may be effective in treating a subset of KRAS mutant lung cancers." (PMID 25992771, 2015). "Although many molecular genetic studies have implicated certain genetic mutations in non-small cell lung cancer (NSCLC), including mutations in the EGFR, PIK3CA, BRAF, KRAS, and ALK genes, only a few studies have focused on the genetic events associated with salivary gland-type lung carcinomas." (PMID 26373952, 2015). "Such downstream targets were previously shown to be involved in not only in the development of lung cancers with KRAS mutations, but also of those without KRAS mutations." (PMID 24503901, 2014). "Furthermore, the increased tumor progression seen in a KRAS-driven lung cancer model upon HIF2a depletion (i.e., HIF2a as a tumor suppressor) is in line with the CSPG4’s lack of pro-malignant features." (PMID 24932730, 2014). "Lung cancer is the major cause of cancer-related deaths and many cases of Non Small Cell Lung Cancer (NSCLC), a common type of lung cancer, have frequent genetic/oncogenic activation of EGFR, KRAS, PIK3CA, BRAF, and others that drive tumor growth." (PMID 25466244, 2014).
lung cancer (continued). "Another alternative approach to targeting KRAS-driven lung cancers through RNA interference technology, is to identify and consequently silence the gene products whose inhibition may lead to cell death only in the presence of KRAS mutations." (PMID 25593996, 2014). "This enabled us to draw metabolic portraits characterizing KRAS mutant clones in lung cancer cells." (PMID 24952473, 2014). "Although the EGF receptor tyrosine kinase inhibitors (EGFR-TKI) gefitinib have shown dramatic effects against EGFR mutant lung cancer, patients become resistant by various mechanisms, including gatekeeper EGFR-T790M mutation, MET amplification, and KRAS mutation, thereafter relapsing." (PMID 24939055, 2014). "In pancreatic cancer, KRAS promotes growth transformation and invasion of immortalized human pancreatic cells by Raf and PI3K signaling, while the same mutation in mice causes early onset lung cancer." (PMID 25361007, 2014). "The cell cycle upon KRAS knockdown was determined in the two lung cancer cell lines to examine whether the effects were comparable with those of the KRAS mutated breast cancer cell line MDA-MB-231." (PMID 24368337, 2014). "Furthermore, in different breast and lung cancer cell lines an inhibitory effect of miR-200c-dependent KRAS silencing on proliferation and cell cycle was demonstrated." (PMID 24368337, 2014). "Our finding that AZD6244 was effective in one distinct KRAS mutant human lung cancer NCI-H460 models supports and validates this hypothesis." (PMID 24939055, 2014). "Furthermore, the inhibitory rffect of miR-200c-dependent KRAS silencing on proliferation and cell cycle was demonstrated in dfferent breast and lung cancer cell lines." (PMID 24368337, 2014). "GDC-0980 was reported to be a potent inhibitor of breast, prostate and lung cancer cell growth and was much less effective against melanoma and pancreatic cancers, most likely due to the presence of highly active KRAS and BRAF usually encountered in these cancers." (PMID 25221930, 2014). "Some pilot studies have reported that intrinsic factors in EGFR-mutant lung cancer cells, such as mutations in T790M, PI3CA, or KRAS and activation of the intracellular Fas/NF-κB signaling pathway, may confer primary resistance to EGFR TKIs." (PMID 24376677, 2013). "Recent clinical studies have demonstrated that MET amplification predicts that patients with lung cancer and activating EGFR mutations will fail to respond to erlotinib or gefitinib, and KRAS mutation predicts that patients with colon cancer will fail to respond to cetuximab." (PMID 23577104, 2013). "For instance, Hexokinase2 (HK2), an enzyme catalyzing the first committed step of glucose metabolism, has recently been shown to be required for tumor initiation and maintenance by using mouse models of KRas-driven lung cancer and ErbB2-driven breast cancer with Hk2 conditional knockout." (PMID 24318446, 2013). "Whereas EGFR mutations tend to occur more frequently in never-smokers with lung cancer, the presence of KRAS mutations cannot be easily predicted based on smoking status alone." (PMID 27234388, 2013). "Other studies showed the presence of KRAS mutations in lung cancer to be indicative of worse outcome regardless of the treatment they received." (PMID 23922984, 2013). "Clinical trials are ongoing in lung cancers carrying PIK3CA, BRAF or KRAS mutations." (PMID 24236184, 2013). "EGFR gene mutations, KRAS gene mutations, EML4-ALK rearrangements and altered MET signaling are widely recognized alterations that play important roles in both the biological mechanisms and the clinical sensitivity to treatment in lung cancer." (PMID 27234388, 2013).